PFKP (phosphofructokinase, platelet)
Description:
Catalyzes the phosphorylation of D-fructose 6-phosphate to fructose 1,6-bisphosphate by ATP, the first committing step of glycolysis.
Synonyms: ATP-PFK; PFK-P; PFK-C; PFKF
Tractability: Small molecule: a structure with a bound ligand is known. PROTAC: ubiquitination databases record sites on it; its protein half-life has been measured; a small molecule that binds it is known.
Target class: Enzyme
Gene: Protein-coding gene on chromosome 10 (3,066,333 to 3,137,723, forward strand). Ensembl gene ENSG00000067057.
Subcellular location: Cytoplasm
Subcellular location (Human Protein Atlas): Cytosol
Pathways (Reactome):
Metabolism: Glycolysis
Gene Ontology:
Molecular function: 6-phosphofructokinase activity; cadherin binding; protein binding; protein-containing complex binding; fructose-6-phosphate binding; ATP binding
Biological process: canonical glycolysis; fructose 1,6-bisphosphate metabolic process; fructose 6-phosphate metabolic process; glycolytic process
Cellular component: cytoplasm; cytosol; extracellular exosome; membrane; nucleus; 6-phosphofructokinase complex
Genetic constraint (gnomAD): Loss-of-function variants: 72 observed, 68.14 expected, observed/expected ratio (o/e) 1.06, 90% interval 0.87 to 1.29. The synonymous counts are far from expectation, so gnomAD's model fits this gene poorly and the ratio says little. Missense variants: 953 observed, 927.91 expected, observed/expected ratio (o/e) 1.03, 90% interval 0.97 to 1.08. Synonymous variants: 490 observed, 375.93 expected, observed/expected ratio (o/e) 1.3, 90% interval 1.21 to 1.4.
Homologues: Orthologues: chimpanzee PFKP (99% identical), macaque PFKP (94% identical), rabbit PFKP (92% identical), dog PFKP (92% identical), guinea pig PFKP (91% identical), pig PFKP (90% identical), mouse Pfkp (88% identical), rat Pfkp (88% identical), tropical clawed frog pfkp (81% identical), zebrafish pfkpb (79% identical), zebrafish pfkpa (78% identical), Drosophila melanogaster Pfk (59% identical), and 1 more. Paralogues in human: PFKM (71% identical), PFKL (67% identical).
Diseases named in the same sentence as PFKP in open-access papers:
PFKP is named in the same sentence as 87 diseases in open-access papers, as found by Europe PMC text mining. Sharing a sentence is not in itself a finding about the gene and the disease. The quoted sentences say what the papers report.
breast cancer (42 papers, 2013 to 2026). A primary or metastatic malignant neoplasm involving the breast. "Upregulation of PFKP is strongly associated with tumor progression and is a significant indicator of an unfavorable prognosis in breast cancer, glioblastoma, and leukemia." (PMID 38982480, 2024). "The platelet form of PFK1 (PFKP) is overexpressed in breast cancer cells and has been associated with increased glycolytic efficiency." (PMID 34298660, 2021). "Breast cancer is characterized by high PFKP expression that, in turn, has been associated with decreased patient survival." (PMID 33588886, 2021). "Clinically, NSCLC and breast cancer tumors display PFKP upregulation, and high PFKP expression is associated with shorter patient survival in both cancers." (PMID 34367973, 2021). "Association of PFKP protein level with different clinicopathological features of 160 breast cancer patients." (PMID 32470015, 2020). "The rate-limiting enzyme PFKP was previously reported dysregulated in different cancers and the clinical significance of PFKP has been involved in various cancers, however, the clinical association of PFKP in breast cancer was still unclear." (PMID 32470015, 2020). "Since PFKP was upregulated in breast cancer and negatively associated with the prognostic of breast cancer patients, it had the potential to be a drug target." (PMID 32470015, 2020). "Our investigation also revealed that other isoforms of phosphofructokinase, i.e., PFKL and PFKM, do not play important roles in promoting breast cancer progression as only high PFKP gene expression is associated with poor survival in breast cancer patients." (PMID 29069720, 2017). "Our results demonstrated that WNT5A signaling causes a reduced production of lactate in breast cancer cells in parallel with reduced cellular migration and down-regulation of PFKP." (PMID 29069720, 2017). "Phosphofructokinase platelet-type (PFKP) protein expression was positively associated with nodal expansion, estrogen receptor and progesterone receptor negativity, and overall reduced survival of breast cancer patients." (PMID 33401572, 2021). "Importantly, the expression levels of PFKP were demonstrated to associate with poor survival of patients with breast cancer." (PMID 32470015, 2020). "Meanwhile, overexpression of PFKP may serve as an independent poor prognostic factor for patients with breast cancer, which provides an important basis for targeting PFKP in breast cancer patients with BRCA1 or ZBRK1 deficiency." (PMID 32470015, 2020). "Furthermore, when we overexpressed BRCA1 in HCC1937 cell line (a BRCA1 deficient breast cancer cell line), there was a notable suppression of PFKP expression in both protein and mRNA level upon BRCA1 overexpression." (PMID 32470015, 2020). "Importantly, the clinical relevance study revealed that the expression of PFKP was significantly associated with poor prognosis of patients with breast cancer (BC) and related with different subtypes of BC." (PMID 32470015, 2020). "The current study showed that PFKP promotes tumor metastasis through hypoxia-mediated altered glycolysis and can be a potential prognostic marker used to identify breast cancer metastasis." (PMID 40821334, 2025). "For example, KLF4 activates the transcription of the PFKP gene by directly binding to the PFKP promoter, playing a critical role in cell proliferation in breast cancer cells." (PMID 38982480, 2024).
breast cancer (continued). "It has been broadly reported that PFKP expression is elevated in many cancers and is correlated with worse prognosis in breast cancer, leukemia, lung cancer, and HCC." (PMID 37242427, 2023). "PFKP was reported to be highly expressed in different cancers, including breast cancer, clear cell renal cell carcinoma, lung cancer, and glioblastoma, and associated with the increase in glycolysis." (PMID 36831193, 2023). "Among these isoforms, PFKP is frequently abnormally expressed in lung cancer, breast cancer, kidney cancer, and oral squamous cell carcinoma and has a poor effect on cancer behavior 23-26." (PMID 37151384, 2023). "In breast cancer, PFKP expression was negatively correlated with estrogen receptor and human epidermal growth factor receptor-2 and positively correlated with transforming growth factor-β and MYC expression." (PMID 37151384, 2023). "More recently, studies have shown that PFKP is involved in the initiation and progression of multiple cancer types, such as lung cancer, breast cancer, glioblastoma, T-cell acute lymphoblastic leukemia, and prostate cancer." (PMID 37833332, 2023). "Under hypoxic conditions, breast cancer cells accumulate citrate through upregulation of PFKP and citrate synthase, and cytoplasmic citrate promotes breast cancer cell migration, invasion, and metastasis." (PMID 37444501, 2023). "PFKP has been reported to have multiple functions in different cancer types, including lung cancer and breast cancer." (PMID 37833332, 2023). "Previous research has shown that PFKP is abnormally expressed in lung cancer, breast cancer, prostate cancer, and glioblastoma." (PMID 37833332, 2023). "The expression level of PFK is elevated in several cancers, such as breast cancer, PCa, and lung cancer; the expression of phosphofructokinase platelet (PFKP), an isoform of PFK, is associated with poor prognosis of breast cancer." (PMID 35335873, 2022). "These experiments identified PFKP as one of the candidate substrates of HRD1 in breast cancer cells." (PMID 33588886, 2021). "Mechanistically, HRD1 interacted and colocalized with PFKP in the cytoplasm, targeted PFKP for ubiquitination and degradation, and ultimately reduced PFKP expression and activity in breast cancer cells." (PMID 33588886, 2021). "The Hrd1 and PFKP protein levels were negatively correlated in breast cancer tissues (P < 0.001 by Spearman’s correlation test)." (PMID 33588886, 2021). "The role of PFKP in breast cancer tumorigenesis was investigated by intracranial injection of MDA-MB-231 cells stably expressing HRD1, with or without overexpression of PFKP, into athymic nude mice." (PMID 33588886, 2021). "Deletion of PFKP can significantly inhibit lactate production to impair invasion and migration by breast cancer cells." (PMID 33588886, 2021). "The role of PFKP in HRD1-mediated breast cancer inhibition was investigated by overexpressing PFKP in MDA-MB-231 cells stably expressing exogenous HRD1." (PMID 33588886, 2021). "HRD1 inhibited glycolysis and tumor growth and metastasis through direct inhibition of PFKP expression in breast cancer cells." (PMID 33588886, 2021). "Here, our mass spectrometry analyses identified an interaction between HRD1 and PFKP, the rate-limiting enzyme in glycolysis, in breast cancer cells." (PMID 33588886, 2021). "Accumulating evidence has demonstrated that PFKP plays a crucial role in promoting aerobic glycolysis and lactate production in breast cancer cells, thereby stimulating cancer cell proliferation and metastasis." (PMID 33588886, 2021). "PFKP is overexpressed in breast cancer and promotes the Warburg effect, and PFKP expression and activity are mainly regulated by post-translational modifications." (PMID 33588886, 2021). "Mass spectrometry analysis results revealed a large HRD1 interactome, which included PFKP (platelet isoform of phosphofructokinase), a critical enzyme involved in the Warburg Effect in breast cancer." (PMID 33588886, 2021).
breast cancer (continued). "However, the mechanism underlying the regulation of PFKP stability in breast cancer is unknown." (PMID 33588886, 2021). "In summary, our results indicate that BRCA1/ZBRK1 affects the transcriptional regulation of PFKP, providing important evidence for the understanding of abnormal mechanism of breast cancer glycolysis." (PMID 32470015, 2020). "The present study aims to elucidate the underlying mechanism how PFKP is regulated by BRCA1 and the clinical significance of PFKP in breast cancer." (PMID 32470015, 2020). "Collectively, these findings indicated that the expression levels of both protein and mRNA of PFKP were promising prognostic factors for clinical practice of breast cancer." (PMID 32470015, 2020). "To determine the significance of PFKP in patients with breast cancer, we first used immunohistochemistry assay to determine the expression levels of PFKP in tissue microarray containing 160 breast cancer (BC) tissue specimens and 10 adjacent normal tissues." (PMID 32470015, 2020). "Recently, PFKP was noted to have an aberrant upregulation in many cancers, such as breast cancer, prostate cancer, and glioblastoma." (PMID 33344071, 2020). "Previous studies have shown that PFKP was closely related with invasion and migration ability of breast cancer cells." (PMID 32470015, 2020). "In previous reports, PFKP was found to be associated with malignancy of some types of tumors, including breast cancer, which was further confirmed by our findings that PFKP was overexpressed in a subset of breast cancer tissues." (PMID 32470015, 2020). "Although PFKP is a key regulatory enzyme in glycolysis and gluconeogeneis pathways, only four PubMed abstracts were found targeting this gene in breast cancer research." (PMID 31231467, 2019). "Significant reductions in lactate production were observed in both PFKP-silenced breast cancer cell lines (MDA-MB-468 and MDA-MB-231) as compared to their respective control cells (NC)." (PMID 29069720, 2017). "We next tested if direct inhibition of β-catenin signaling in breast cancer cells will result in decreased PFKP protein expression." (PMID 29069720, 2017). "We demonstrated that PFKP-silenced breast cancer cells exhibited reduced lactate production as well as impaired breast cancer cell migration and invasion." (PMID 29069720, 2017). "To investigate the functional role of PFKP in breast cancer cells, we next investigated how the reduced expression of PFKP affects breast cancer cell migration and invasion." (PMID 29069720, 2017). "Our initial findings revealed that WNT5A signaling impairs lactate production in breast cancer cells and that PFKP expression relates to prognosis of breast cancer patients." (PMID 29069720, 2017). "Overall, these results indicate that the expression of PFKP not only relates to the glycolytic activity but also to breast cancer patient prognosis." (PMID 29069720, 2017). "To further investigate the functional role of PFKP in breast cancer cells, we knocked down PFKP expression using specific siRNAs (as described in the Materials and Methods section)." (PMID 29069720, 2017). "WNT5A signaling inhibits aerobic glycolysis in breast cancer cells via a β-catenin-PFKP axis resulting in reduced lactate production." (PMID 29069720, 2017). "We next examined if PFKP silencing affected lactate production in parental breast cancer cell lines." (PMID 29069720, 2017).
breast cancer (continued). "WNT5A expression significantly reduced PFKP expression in both breast cancer cell lines (i.e., MDA-MB-468-5A and MDA-MB-231-5A) compared to their respective EV-transfected control cells." (PMID 29069720, 2017). "Using a siRNA knockdown approach, we demonstrated that PFKP plays a crucial role in regulating aerobic glycolysis in breast cancer cells." (PMID 29069720, 2017). "Krüppel-like factor 4 (KLF4) overexpression increased PFKP expression as well as glycolytic activity in breast cancer cell lines." (PMID 27049827, 2016). "Another study reported that activation of PFKP (6-phosphofructokinase type C), which is downregulated in SASP-treated PEL cells is closely associated with breast cancer cell proliferation." (PMID 25860939, 2015). "Disrupting this axis-for instance, by PFKP inhibition or CXCL16/CXCR6 blockade-may restore TA sensitivity in aggressive basal-type breast cancer, offering a promising strategy to improve long-term outcomes for hard-to-treat patients." (PMID 42024199, 2026). "Notably, ubiquitin-specific protease 5 (USP5), a deubiquitinating enzyme, has been shown to stabilize the PFK-1 platelet isoform (PFKP) and upregulate its expression in breast cancer cells, thereby promoting glycolytic flux and supporting tumor metabolism." (PMID 40303296, 2025). "qRT-PCR confirmed PFKP (p < 0.001) and Ki67 (p < 0.001) upregulation in 100 breast cancer samples." (PMID 40821334, 2025). "Our pancancer GSEA also revealed a significant positive correlation between PFKP and EMT, suggesting that PFKP may also be involved in tumor metastasis, which was in accordance with previous research in breast cancer and T-cell acute lymphoblastic leukemia." (PMID 37833332, 2023). "Both KLF4 and HIF-1α can activate PFKP gene transcription in breast cancer." (PMID 37444501, 2023). "Decreased PFKP expression significantly suppressed breast cancer cell growth and invasion." (PMID 37151384, 2023). "Increased PFKP expression and activity are related to neoplastic activity, metastasis, and decreased survival in several types of cancer, primarily brain, kidney, and breast cancers." (PMID 37326348, 2023). "PFKP is a platelet-specific phosphofructokinase that makes a critical difference in metabolic reprogramming in certain cancers, including bladder cancer, breast cancer, and lung cancer, and is a potential driver gene in the GEO (Gene Expression Omnibus) database." (PMID 36404333, 2022). "PFKP has been shown to enhance EMT in breast cancer cells under hypoxic culture conditions." (PMID 34367973, 2021). "Therefore, HRD1 appeared to inhibit aerobic glycolysis, growth, migration, and invasion of breast cancer cells by downregulating PFKP." (PMID 33588886, 2021). "Therefore, suppression of PFKP expression and activity represents a viable strategy for breast cancer treatment." (PMID 33588886, 2021). "In addition, Peroxisome proliferator-activated receptor gamma (PPARγ) was overexpressed in BRCA1-defective breast cancer patients, and in vascular smooth muscle cells PPARγ was found to regulate PFKP." (PMID 32470015, 2020). "Our study provided a new insight into the dysregulation of glycolysis in breast cancer, which might be partially due to the deficiency of BRCA1/ZBRK1 axis and subsequently reversed the transcriptional repressive effect on PFKP." (PMID 32470015, 2020). "The luminal types of breast cancer consist of the pentose phosphate pathway (PPP) subset by suppression of PFKP while the basal-like subtype (also known as triple negative breast cancer, TNBC) mainly utilizes glycolysis and mitochondrial fatty acid oxidation (FAO) by loss of FBP1 and ACC2." (PMID 32927665, 2020). "Knockdown of PFKP stimulates survival of breast cancer cells." (PMID 32612536, 2020). "We also found that PFKP overexpressed in a subset of breast cancer patients and could serve as a prognostic factor, which represented a potential target for BC therapy." (PMID 32470015, 2020).